GPC2 (glypican 2)
Diseases named in the same sentence as GPC2 in open-access papers (continued):
Sharing a sentence is not in itself a finding about the gene and the disease.
childhood cancers (4 papers, 2021 to 2022). "GPC2-201, encoding the longest form of GPC2 protein that contains exons 1–10 with 5 hypothetic HS chains, is the isoform overexpressed in pediatric cancers." (PMID 34195677, 2021). "Increasing evidence has demonstrated the overexpression of GPC2 in neuroblastoma, a kind of childhood cancer." (PMID 35345673, 2022). "GPC2 plays an important role in neural cell adhesion and neurite growth, and researchers have found that GPC2 is a powerful candidate target for immunotherapy in childhood cancer." (PMID 35233466, 2022). "As one of several mRNA transcripts, GPC-2 is highly expressed in several childhood cancers." (PMID 33902495, 2021). "A research identified immunotherapy targets in 12 pediatric cancers, and GPC2 was analyzed in 8 diseases such as osteosarcoma (OS) and Ewing sarcoma (EWS), which makes it evident that GPC2 has a wide range of functions in childhood cancers." (PMID 35345673, 2022).
glioma (4 papers, 2022 to 2025). A benign or malignant brain and spinal cord tumor that arises from glial cells (astrocytes, oligodendrocytes, ependymal cells). "We validated results from a previous study, in which mRNA electroporation was used to transiently express GPC2-CARs to target GPC2+ high-grade glioma and MB." (PMID 41159102, 2025). "To demonstrate this, we functionally validated the potential of ECM-targeting CAR T cell therapy by evaluating the efficacy of GPC2-targeting CARs against an adult and pediatric glioma model." (PMID 40517137, 2025). "Genes associated with the neuronal differentiation pathway (Pcsk9, Runx1, Cebpb, Fzd4, Wnt7a, Ascl1, Fzd2, Edn3, Olig2, and Gpc2), gliomas (Shc1, Cdk4, E2f2, and Ccnd1), and cell cycle (Bub1b, Bub, Ccnb1, Ccnb2, and Cdc20) were significantly downregulated." (PMID 36147849, 2022). "Given that GPC2 ranked as the 14th highest target in adult gliomas, we determined if low-affinity GPC2 CAR T cells could also target adult GBM, and therefore conducted functional testing against U251 GBM cells in an in vitro cytotoxicity assay." (PMID 40517137, 2025). "More broadly, our findings underscore the therapeutic potential and relevance of ECM components such as GPC2, CSPG4, and PTPRZ1 as novel pan-glioma immunotherapy targets." (PMID 40517137, 2025). "In ETMR, pathology scores ranged from 0 to 3+, while high-grade gliomas showed no detectable GPC2 expression." (PMID 41159102, 2025). "Interestingly, we did not detect GPC2 in high-grade gliomas using our scFv, CT3, which binds to the cancer-specific exons 3 and 10 of GPC2." (PMID 41159102, 2025).
osteosarcoma (4 papers, 2021 to 2025). A usually aggressive malignant bone-forming mesenchymal neoplasm, predominantly affecting adolescents and young adults. "The data revealed appreciable GPC2 mRNA expression in osteosarcoma, rhabdomyosarcoma, and high-grade sarcoma in addition to NB." (PMID 34195677, 2021).
pancreatic cancer (4 papers, 2015 to 2023). "For example, GPC1, the same subfamily gene of GPC2, has been proved to be a diagnostic biomarker and therapeutic target for pancreatic cancer and trigger a wave of interest of glypicans." (PMID 35345673, 2022). "In this regard, HS20 may be useful for multiple tumor types by targeting different glypicans, such as GPC1 in pancreatic cancer, GPC2 in pre-B cell ALL, and GPC5 in rhabdomyosarcoma." (PMID 26332121, 2015). "A gating of only EVs between 110-150nm meant to enumerate GPC1+ve, GP2+ve or GPC2 and GP2 dual positive exosomes (small EVs) also failed to distinguish between patients with BPD and pancreatic cancer." (PMID 30800217, 2019).
prostate carcinoma (4 papers, 2020 to 2024). A carcinoma that arises from epithelial cells of the prostate gland. "To investigate the potential molecular mechanism underlying the effect of GPC2 on cell proliferation, migration, and invasion, we employed bioinformatic analysis on the gene expression matrix of the prostate cancer tissues in TCGA database." (PMID 39014225, 2024). "In vitro experiments revealed that overexpression of GPC2 promoted cell proliferation, migration, and invasion in prostate cancer cells and silence of GPC2 caused the opposite effects." (PMID 39014225, 2024). "Thus, our loss-and-gain of function experiments illustrated that GPC2 promoted prostate cancer cell proliferation, migration, and invasion in vitro." (PMID 39014225, 2024). "First, GPC2 expression in prostate cancer tissues should also be examined by experiments to make our result more convincing." (PMID 39014225, 2024). "Decreased expression of GPC2 inhibited cell proliferation, migration, and invasion in prostate cancer, whereas GPC2 overexpression promoted these properties." (PMID 39014225, 2024). "A real-world cohort of prostate cancer patients needs to be collected to further test the predictive ability of GPC2 in prostate cancer." (PMID 39014225, 2024). "Through data mining using online tool and bioinformatic methods, we found the GPC2 was upregulated in prostate cancers and its higher expression predicted poor patients’ prognosis." (PMID 39014225, 2024). "GPC2 promotes prostate cancer cell proliferation, migration, and invasion via MDK-mediated activation of PI3K/AKT signaling pathway." (PMID 39014225, 2024). "Higher expression of GPC2 was correlated with higher Gleason score, lymphatic metastasis, and worse overall survival in prostate cancer patients." (PMID 39014225, 2024). "IHC analysis also confirmed that the protein level of GPC2 was higher in prostate cancer tissues than that in normal tissue." (PMID 39014225, 2024). "GPC2 promoted prostate cancer cell proliferation, migration, and invasion via MDK-mediated activation of PI3K/AKT signaling pathway." (PMID 39014225, 2024). "Then, using the UALCAN database, we also found a significant higher expression of GPC2 in prostate cancer tissues compared to that in normal tissues." (PMID 39014225, 2024). "Then, we manipulated the expression of MDK through plasmid transfection in prostate cancer cell lines that were stably knocking down of GPC2, and further measured the protein levels of PI3K, p-PI3K, AKT, as well as p-AKT." (PMID 39014225, 2024). "Taken together, these results indicated that silence of GPC2 depleted the malignancy of prostate cancer cells." (PMID 39014225, 2024). "In this work, our findings revealed that GPC2, which was higher in prostate cancer than that in adjacent normal tissue, was positively correlated with clinical stage and lymphatic metastasis in prostate cancer." (PMID 39014225, 2024). "The TCGA prostate carcinoma dataset was separated into GPC2High and GPC2Low groups based on the median expression level of GPC2, the differentially expressed genes (DEGs) among the two groups were identified using bioinformatic method." (PMID 39014225, 2024). "Kaplan-Meier survival analysis indicated that higher expression of GPC2 predicted worse clinical outcome in patients with prostate cancer, suggesting a potential role of GPC2 in prognostic prediction in prostate cancer." (PMID 39014225, 2024). "Our results indicated that GPC2 served as an oncoprotein in prostate cancer, and the knockdown of GPC2 impaired the abilities of cell proliferation, migration, and invasion, while overexpression of GPC2 had the opposite effect." (PMID 39014225, 2024). "Second, in vivo experiments needed to be performed to investigate the inhibitory effect of GPC2-based target therapy in prostate cancer." (PMID 39014225, 2024).
prostate carcinoma (continued). "To further explore the function of GPC2, we first silenced the expression of GPC2 in prostate cancer cells (DU145 and PC-3) through lentivirus infection and performed a series of function studies." (PMID 39014225, 2024). "Take together, our results indicated that overexpression of MDK could reverse the inhibitory effect of GPC2 knockdown on malignancy of prostate cancer." (PMID 39014225, 2024). "There studies indicated that GPC2 might be an ideal therapeutic target in cancer, while GPC2 role in prostate cancer remains unclear." (PMID 39014225, 2024). "In all, our study identified GPC2 as an oncogene in prostate cancer." (PMID 39014225, 2024). "In summary, our study identified GPC2 as an oncoprotein in prostate cancer." (PMID 39014225, 2024). "Our study provides a scientific basis for finding novel target therapy methods in prostate cancer and the GPC2/MDK/PI3K/AKT signaling axis might be promising therapeutic target." (PMID 39014225, 2024). "ROC curve analysis showed that the AUC value was 0.796, suggesting GPC2 might be served as a biomarker to predict prostate cancer prognosis." (PMID 39014225, 2024). "In the present study, we demonstrated that GPC2 was an oncogene in prostate cancer." (PMID 39014225, 2024). "To simplify, our research reveals that GPC2 promotes prostate cancer progression via MDK-mediated activation of PI3K/AKT signaling pathway, and GPC2 might be a potential therapeutic target in prostate cancer." (PMID 39014225, 2024). "To explore whether GPC2 promotes the activation of PI3K/AKT signaling via MDK in prostate cancer, we first confirmed the physical interaction between GPC2 and MDK through immunoprecipitation assay." (PMID 39014225, 2024). "To detect whether there were association between GPC2 and PI3K/AKT signaling, we examined the expression level of PI3K, p-PI3K, AKT, and p-AKT in prostate cancer cells by western blot assay." (PMID 39014225, 2024). "Here, we revealed a novel action of GPC2 and a tumor promoting mechanism in prostate cancer." (PMID 39014225, 2024). "GPC2 was upregulated in prostate cancer tissues and cell lines." (PMID 39014225, 2024). "Whereas, to date, the GPC2 role in prostate cancer remains unreported." (PMID 39014225, 2024). "We also explored the effect of GPC2 overexpression on the malignancy of prostate cancer cells." (PMID 39014225, 2024). "GPC2 might be a promising prognosis predictor and potential therapeutic target in prostate cancer." (PMID 39014225, 2024). "The rescue assay results in prostate cancer cells demonstrated that overexpression of MDK could attenuate GPC2 knockdown induced inactivation of PI3K/AKT signaling and partly reverse GPC2 knockdown induced inhibition of cell proliferation, migration, and invasion." (PMID 39014225, 2024). "Taken together, these in vitro experiment results that we have presented so far indicated that GPC2 might be a potential therapeutic target in prostate cancer, further exploration should be conducted in vivo to confirm the anti-tumor efficiency of GPC2-based target therapy." (PMID 39014225, 2024). "Finally, to investigate whether GPC2 knockdown inhibited the malignancy of prostate cancer via MDK, we upregulated the expression of MDK in DU145 and PC-3 cells that were stably knocking down of GPC2, and performed functional assays." (PMID 39014225, 2024). "Moreover, rescue experiments showed that overexpression of MDK could attenuate the inhibitory effect of GPC2 knockdown on prostate cancer proliferation, migration, and invasion." (PMID 39014225, 2024). "A ceRNA network analysis of prostate cancer established a network consisting of four hub genes, homeobox B5 (HOXB5), glypican 2 (GPC2), pepsinogen A-5 (PGA5), and ameloblastin (AMBN), which are strongly associated with patient survival." (PMID 34681112, 2021).
prostate carcinoma (continued). "Further experiments confirmed that GPC2 positively regulated PI3K/AKT signaling though MDK, and overexpression of MDK attenuated the inhibitory effect of GPC2 knockdown on malignant behaviors of prostate cancer." (PMID 39014225, 2024). "Nevertheless, there have been no investigations of GPC2 and its regulatory mechanism in prostate cancer." (PMID 39014225, 2024).
bladder cancer (2 papers, 2021 to 2024). "FASN, MAP2 and BMP6 were highly expressed in bladder cancer, while GPC2, CNOT6L, GALNT12 and CARD10 were expressed at low levels in bladder cancer." (PMID 38218866, 2024). "Among these five genes (GPC2, SETBP1, FGF11, APOL1, H1–2) related to the prognosis of patients with BC, there are no reports or experiments about these genes related to bladder cancer, except for H1–2." (PMID 34315402, 2021).
colon adenocarcinoma (2 papers, 2022 to 2024). "GPC2 was shown to be highly expressed in colon adenocarcinoma (COAD) and was associated with advanced tumor stage and poor prognosis." (PMID 39014225, 2024). "However, the role of GPC2 in colon adenocarcinoma (COAD) remains to be further investigated." (PMID 35233466, 2022).
embryonal cancers (2 papers, 2021 to 2025). A non-seminomatous malignant germ cell tumor characterized by the presence of large germ cells with abundant cytoplasm resembling epithelial cells, geographic necrosis, high mitotic activity, and pseudoglandular and pseudopapillary structures formation. "Overall, these data show that GPC2 is highly expressed in MB and RB, indicating GPC2 as a potential target in these aggressive pediatric embryonal cancers." (PMID 34195677, 2021).
glioblastoma (2 papers, 2020 to 2025). The most malignant astrocytic tumor (WHO grade IV). "A consensus clustering algorithm analysis of the 3909 protein groups detected in all the tumor samples identified two stable proteomic subtypes for IDH wild-type GBM: glioblastoma proteome cluster 1 (GPC1, N = 26) and GPC2 (N = 13)." (PMID 32620753, 2020).
Infertility (2 papers, 2024 to 2025). "Exome sequencing analyses in the UK Biobank (N=197,340) revealed that women carrying testosterone-lowering rare variants in GPC2 were at higher risk of infertility (OR=2.63, P=1.25E-03)." (PMID 38562841, 2024). "Although there was evidence for distinct genetic architectures of infertility and reproductive hormones, we showed that individual genes containing rare protein-coding variants associated with testosterone (GPC2, CYP3A43 and TRIM4) were also associated with higher risk of infertility in the UKBB." (PMID 40229599, 2025). "Although there was evidence for distinct genetic architectures of infertility and reproductive hormones, we showed that individual genes containing rare protein-coding variants associated with testosterone (GPC2, CYP3A43, TRIM4) were also associated with higher risk of infertility in the UK Biobank." (PMID 38562841, 2024).
leukemia (2 papers, 2022). A malignant (clonal) hematologic disorder, involving hematopoietic stem cells and characterized by the presence of primitive or atypical myeloid or lymphoid cells in the bone marrow and the blood. "To address the question of persistence, we further characterized the BiCisCAR T cells in vivo by measuring the proportion of CAR T cells in mouse spleens 21 days after CAR T cell infusion in our model of NALM6 leukemia cells expressing either GPC2 or CD276." (PMID 35852863, 2022). "A particularly striking example of BiCisCAR T cells’ ability to prevent tumor escape was demonstrated with a heterogeneous metastatic model, where NALM6 leukemia cells expressing either GPC2 or CD276 were mixed in a 1:1 ratio and injected into mice." (PMID 35968786, 2022). "Importantly, in vivo imaging showed that both 2.5 × 106 and 5 × 106 doses of BiCisCAR T cells completely eradicated leukemia expressing GPC2 or CD276 and prevented the recurrence of leukemia." (PMID 35852863, 2022). "Both GPC2 and CD276 CAR T cells failed to control tumor growth, due to the dominance of CD276+ and GPC2+ cells respectively, whereas the BiCisCAR T cells were able to completely eradicate leukemia and prevent recurrence." (PMID 35968786, 2022).
medulloblastoma (2 papers, 2021 to 2025). A malignant, invasive embryonal neoplasm arising from the cerebellum. "GPC2-CAR T cells regress GPC2+ medulloblastoma when delivered intravenously or intraventricularly in preclinical orthotopic models." (PMID 41159102, 2025). "Previous studies have shown that GPC2 is also expressed in medulloblastoma." (PMID 41159102, 2025). "Moreover, GPC2 levels were elevated in 78% of medulloblastoma (MB) tissues (7/9) compared with normal brain samples." (PMID 34195677, 2021).
basal cell carcinoma (1 paper, 2022). A carcinoma involving the basal cells. "Furthermore, the genes coexpressed with GPC2 in COAD tissues were significantly enriched in basal cell carcinoma, Notch signaling pathway, and Hedgehog signaling pathway." (PMID 35233466, 2022).
choroid plexus carcinoma (1 paper, 2023). A malignant neoplasm arising from the choroid plexus. "Expression and CNV analyses demonstrated that GPC2 is a highly expressed and copy-number-gained immunotherapeutic target in ETMRs, MBs, choroid plexus carcinomas, H3 WT HGGs, and DMGs." (PMID 37492101, 2023).
cognitive decline (1 paper, 2025). "Among the genes induced in excitatory neurons of PWH were ADAMTS2, whose over-expression predicts cognitive decline in AD42 and GPC2 that is upregulated in AD43." (PMID 41282152, 2025).
cognitive deficits (1 paper, 2025). "Conversely, the downregulation of genes like NPY, CSPG5, VGF, ADAMTS2 and GPC2 among others, in astrocytes and other cell-types points to impaired neuroprotective mechanisms and compromised synaptic function contributing to cognitive deficits." (PMID 41282152, 2025).
colon cancer (1 paper, 2022). "In view of the role of GPC2 in tumor progression, we explored the role of GPC2 in colon cancer development and progression by bioinformatics analysis and cellular and molecular levels to propose new molecular markers for colon cancer treatment." (PMID 35233466, 2022). "GPC2 can be used as a neuroma immunotherapy target, but it has not been reported in the progression of colon cancer development." (PMID 35233466, 2022).
epilepsy (1 paper, 2020). A brain disorder characterized by episodes of abnormally increased neuronal discharge resulting in transient episodes of sensory or motor neurological dysfunction, or psychic dysfunction. "Other potentially relevant genes displaying the same expression trend were the heparan sulfate proteoglycan GPC2 (a marker of immature neurons), the helix–loop–helix transcription factor ID4 (a marker of postmitotic neurons), and the signaling molecule FGFR3 that has been implicated in epilepsy." (PMID 31820119, 2020).
esophageal squamous cell carcinoma (1 paper, 2022). Esophageal squamous cell carcinoma (ESCC) is a type of esophageal carcinoma (EC) that can affect any part of the esophagus, but is usually located in the upper or middle third. "The amplification of GPC2 accounted for the largest proportion of all mutation types, of which esophageal squamous cell carcinoma, esophagogastric adenocarcinoma, and CHOL had the highest occurrence rates of 8.42%, 6.42%, and 5.56%, respectively." (PMID 35345673, 2022). "Thereinto, the incidence of esophageal squamous cell carcinoma, esophagogastric adenocarcinoma, and CHOL is the highest, which suggests that we should pay attention to the relationship between GPC2 gene mutation and digestive system tumors." (PMID 35345673, 2022).
Hepatitis (1 paper, 2021). Inflammation of the liver. "In the analysis of each subgroup, the mRNA expression of GPC-2 was related to OS with the impact factors of the race (Asian), alcohol consumption, and hepatitis." (PMID 33902495, 2021).
hepatocellular carcinoma (1 paper, 2021). A malignant tumor that arises from hepatocytes. "Lastly, we noticed one shared integrated gene in the current CT3 CAR T cells targeting GPC2, PTPRA, which was also found in the CAR (hYP7) T cells targeting GPC3 in hepatocellular carcinoma from our previous study, although at different integration sites." (PMID 34195677, 2021).